ENSG00000302043 (novel transcript)
Synonyms: LOC124901291
Gene: Long non-coding RNA gene on chromosome 6 (27,703,132 to 27,762,404, reverse strand). Ensembl gene ENSG00000302043.
Gene Ontology:
Molecular function: triplet codon-amino acid adaptor activity
Biological process: translation